CD4 (CD4 molecule)
Diseases named in the same sentence as CD4 in open-access papers (continued):
Sharing a sentence is not in itself a finding about the gene and the disease.
tumor (continued). "CD4+ T cells recovered from GL261-immune C57BL/6 mice were used to detect tumor antigenic determinants presented by the BMDCs with the readout being the number of cells producing IFNγ." (PMID 30400835, 2018). "Categories 1–3 contain CD4+ T cells largely in the tumor stroma with increased frequency distant from the TM." (PMID 30042403, 2018). "Of interest, B cells stimulated by IL-21 are able to kill tumor cells by producing granzyme B. B cells also facilitate CD4+ T cell memory function and CD8+ T cells proliferation." (PMID 29850009, 2018). "This approach elicited tumor antigen-specific CD4+ and CD8+ T cell responses that stalled primary tumor growth and protected against a rechallenge with the parental tumor cells." (PMID 30143632, 2018). "Of note, tumor-infiltrating CD11b+ cells showed comparable expression of MHC class II in the presence of Id-specific CD4+ T cells, indicating that cognate interaction of macrophages with T cells was not impaired in the absence of iNOS." (PMID 30083157, 2018). "In the tumor of mice where the tumor growth was well-controlled by the combination of anti-PD-1/4-1BB or anti-CD4 treatment, DE50 values were significantly lower than those of control." (PMID 29348598, 2018). "Percentages of tumor infiltrating CD4+ and CD8+ T cells and the production of IFN-gamma in CD8+ T cells were significantly enhanced after anti-TIGIT antibody treatment." (PMID 30400822, 2018). "In our cohort, mIHC data showed unequivocally a preferential accumulation of CD8+ T cells within the tumor, and CD4+ T cells in the tumor stroma." (PMID 30042403, 2018). "This is supported by this study showing that elderly tumor-associated CD8+ and CD4+ T cells had reduced IFN-γ, implying reduced effector activity." (PMID 30560130, 2018). "TILs are essential components in the complex landscape of the tumor immune microenvironment, which consists of CD4+ T cells, CD8+ T cells, Tregs, NK cells, B cells, macrophages and DCs." (PMID 30603054, 2018). "We demonstrated that SVX vaccine highly increased tumor infiltration by both CD4+ Tconv and CD8+ T cells." (PMID 30483475, 2018). "In this study, T cells from TCR-transgenic donors with a SCID-background were transferred to recipient mice and tumor challenge led to an activation of tumor-specific CD4 T cells in the draining lymph nodes." (PMID 29032503, 2018). "In a recent study we took advantage of this feature to establish a rodent model with tailored tumor immunogenicity to further elucidate the interplay of autologous CD4 and CD8 T lymphocytes." (PMID 29032503, 2018). "Notch signaling inhibition reduced the IL-22 production by CD4+ T cells from tumor site, and this process was accompanied by down-regulation of AhR mRNA expression, but not RORγt." (PMID 30473538, 2018). "Adoptive transfer of DBY-specific TCR transgenic Marilyn T cells allows monitoring of tumor Ag-specific CD4+ T cell response, mimicking naive T cells that have exited the thymus and encounter tumor Ags in the TdLN." (PMID 29844317, 2018). "Numerous studies emphasize the importance of IFN-γ in tumor suppression, a cytokine that is frequently released by activated CD4 and CD8 T cells." (PMID 29032503, 2018). "Although this study focused on CD8+ T cells, CD4+ T cells, which are classically described as helper T cells, can also exhibit direct anti-tumour cytotoxic function in both mice and humans." (PMID 30001747, 2018). "The inf-DCs have been shown to both activate antigen-specific CD4 T cells and cross-present tumor antigens to activate CD8 T cells, and their presence has been found to be important for the efficacy of cancer immunotherapy." (PMID 30619378, 2018). "Counts of CD4+/PD-1+ tumor-infiltrating lymphocytes had a significant correlation with Ki-67 index that the correlation coefficient was 0.29 (p = 0.001)." (PMID 30069490, 2018).
tumor (continued). "We showed, for CD8 and CD4 markers, a statistically significant correlation between positive cell densities in each tumor region and patient outcome." (PMID 30285868, 2018). "Other tumour-derived biomarkers have been reported recently, including high tumour mutational load, presence of TILs in the tumour microenvironment, increased PD-L1 expression on immune cells, high ratio of CD8+/CD4+ lymphocytes and chromosomal aneuploidy." (PMID 29599916, 2018). "We have characterised further the key contributions of tumour-infiltrating TILs, T effector (CD4+, CD8+), T regulatory (FOXP3+, CTLA-4+) and CD56+ NK cells to pCRs in ALN metastases." (PMID 29390966, 2018). "Cancer-associated fibroblasts have also the potential ability to influence CD4+ Helper T (TH) lymphocytes, switching them from anti-tumor to pro-tumor cells." (PMID 29545811, 2018). "This anti-tumor activity was primarily dependent on CD4+ T cells, and to a lesser extent, CD8+ T cells." (PMID 30563566, 2018). "The use of Salmonella enterica as a tumor antigen carrier in CD4+ and CD8+ T lymphocyte activation is limited to those immunogenic tumors expressing associated or specific tumor antigens." (PMID 30302344, 2018). "It is reported that sunitinib decreased PD-1 expression and increased the infiltration of CD-4+ T cells into the tumor." (PMID 29515799, 2018). "During cancer progression, an increase of Tregs was frequently observed independently of the thymus in blood and tumor margins that suppress CD4 and CD8 T cell responses as well as dendritic cell function." (PMID 29032503, 2018). "Once MMP-9 is inhibited, active CXCR3 ligands would accumulate in tumors and tumor-draining lymph nodes and promote trafficking of new Th1 CD4 T cells and effector CD8 T cells into tumors." (PMID 30500835, 2018). "Sex, CD45+ lymphocyte count, CD4+ or CD8+ lymphocyte count, tumor PD-L1 expression, isocitrate dehydrogenase 1 mutation, and O6 methylguanine-DNA methyltransferase promoter methylation status were not significant factors in both groups." (PMID 29910795, 2018). "We previously showed that increased BTLA expression on tumor-infiltrating CD4+ T cells contributes to T cell suppression in tumor in situ." (PMID 30116751, 2018). "Though the immune function of CD4+/PD-1+ T cells was exhausted in tumor microenvironment, CD4+/PD-1− effector TILs were more metabolically active and proliferative and enriched in immune costimulation gene sets than CD4+/PD-1+ effector TILs from GBM." (PMID 30069490, 2018). "We noted that the anti-tumor effects both at the primary and secondary tumors were largely dependent on CD4 T cells." (PMID 30294332, 2018). "The in vivo study of HNSCC mouse model showed that the A2AR antagonist, SCH58261, not only delayed the tumor growth but also significantly reduced the population of CD4+ Foxp3+ Tregs and increased the anti-tumor response of CD8+ T cells in HNSCC tumors." (PMID 30061885, 2018). "The principal immune cell populations responsible for tumor destruction are the CD3+ tumor infiltrating lymphocytes (TIL) including helper CD4+ and cytotoxic CD8+ lymphocytes while the principal suppressor cell subset is the FOXP3+ T cells." (PMID 30577521, 2018). "Here we sought to determine if CD4 or CD8 lymphocytes are necessary in mediating tumor rejection by HSC + PD-1 therapy." (PMID 30333482, 2018). "We also provided evidences indicating that overexpressed STAT5 combines with TET2 to form complexes that bind to the FOXP3-TSDR, resulting in excessive demethylation in tumor-infiltrating CD4+ T cells." (PMID 30013992, 2018). "On the other hand, whole tumor lysates offer a source of antigens that can elicit a tumor-specific response directed against multiple antigenic epitopes presented to both CD4+ and CD8+ T-cells for generation of long-term memory." (PMID 30149659, 2018).
tumor (continued). "Another immunosuppressive cytokine TGF-β can induce Treg and Th17 cell differentiation from naïve CD4+ T cells as well as polarize both macrophages and neutrophils to support tumor cells." (PMID 29652813, 2018). "For example, transgenic CD4+ lymphocytes that recognize a mutant tumor-specific neoantigen ERBB2 protein induced sustained tumor regression in a patient with cholangiocarcinoma." (PMID 28108950, 2018). "The anti-tumour activity has been attributed to intratumoural Treg depletion or inactivation and CD4 and/or CD8 stimulation." (PMID 29396470, 2018). "Previously, we have shown that CD3+CD4+CD25+ lymphocytes activated by IL-2 killed HLA-negative tumor cells through the FasL-Fas interaction." (PMID 29850628, 2018). "Percentages of tumor infiltrating CD4+ T and CD8+ T cells and the production of interferon gamma (IFN-gamma) were analyzed by flow cytometer." (PMID 30400822, 2018). "Accordingly, chronically activated effector CD4+ T cell expansion and tumor regression are correlated during neo-adjuvant chemotherapy of patients with breast cancer." (PMID 29844317, 2018). "In contrast, the combination of anti-PD-1 or anti-PD-L1 mAbs with an anti-CD4 mAb resulted in a synergistic effect leading to significant increase of tumor-free survival of mice, complete tumor regression, and durable anti-NB immunity." (PMID 30510968, 2018). "Padmanee Sharma’s group demonstrated enhanced expression of the inducible costimulatory molecule (ICOS) on CD4+ T-cells in both peripheral and tumor tissue populations in the setting of neoadjuvant delivery of ipilimumab in urothelial carcinoma." (PMID 30176921, 2018). "Tregs and CD4+Foxp3- cells isolated from tumor infiltrating lymphocytes (TIL) showed comparable frequencies in both strains of mice, however CD8+ T cell frequencies from TIL of IFNARfl/fl x Foxp3YFP-Cre mice were increased." (PMID 29672594, 2018). "This highlights an intriguing role of endogenous MIF as important inhibitory checkpoint in oncogenesis as tumor-derived CD4+ Tregs play an important prooncogenic role by suppressing the immune response to tumor cells." (PMID 29707160, 2018). "Mice depleted of CD4 or CD8 populations showed decreased survival rates after tumor induction compared to immunocompetent mice." (PMID 30305693, 2018). "CD4+ T cells from TILs were significantly more demethylated in the IFNG locus compared to LN (p < 0.0001), whereas the methylation in LNs were higher compared to PBMC, suggesting an increased infiltration of Th1 IFN-γ producing CD4+ T cells into the tumour." (PMID 30075815, 2018). "We previously found that IL-7 selectively expands tumor-reactive CD4 T cells capable of promoting tumor protection in ACT." (PMID 29506153, 2018). "In the tumor, expansion of dominant clones was observed, especially in mice receiving combination anti-PD-1/4-1BB, or anti-CD4 mAb treatment." (PMID 29348598, 2018). "Previously, MDSCs have been shown to mediate CD4+ Foxp3+ Treg development in mouse tumor models in vivo." (PMID 29497426, 2018). "We described a subpopulation of the CD4+CD25+ cytotoxic cells which is able to kill HLA-negative tumor cells; that is, these lymphocytes are involved in the fight against tumor cells that have escaped immune control." (PMID 29850628, 2018). "In order to determine the relevance of these results to tumor recognition, we performed two of the CD4-depleted experiments with additional restimulation groups of live 4T1 tumor cells." (PMID 29618380, 2018). "In spite of a reduction in circulating WBCs, treatment with C alone was associated with the largest tumour infiltration by NK, CD3+CD4+ T cells and m-MDSCs, and with the lowest B cell infiltration." (PMID 29695766, 2018). "The large amount of accumulated evidence indicates that CD4+ T cells have a pivotal role in generating and maintaining anti-tumour immune responses through their interactions with cytotoxic T lymphocytes, B lymphocytes, macrophages and NK cells." (PMID 29490633, 2018).
tumor (continued). "This is the first report of indisputable pTreg conversion and anergy induction of CD4+ T cells in a tumor context." (PMID 29844317, 2018). "Several studies have indicated decreased tumor sizes, reduced CD4+/CD8+ T cell apoptosis, enhanced T cell proliferation and CTL activity, and decreased Treg cell numbers upon IDO silencing, which was confirmed in vitro, in vivo as well as in patient studies." (PMID 29867960, 2018). "TCRs from tumor specific conventional CD4+ T cells and CD8+ T cells were identified using single-cell RT-PCR methods." (PMID 30197648, 2018). "Further, we suppressed the expression of STAT5 by transfection of siRNA-STAT5 and detected the levels of TET2 binding to FOXP3-TDSR in CD4+ T cells from tumor tissues." (PMID 30013992, 2018). "The tumor antigen–specific CD4+ or CD8+ TILs targeting mutant ERBB2IP and KRAS have been shown to have high anticancer activity in patients." (PMID 30409126, 2018). "TILs in the epithelial region, e.g. CD4+ T cells, CD204+ macrophage, and PD-1/PD-L1 expression, appeared to be more closely associated with the WHO grade and European Neuroendocrine Tumour Society (ENETS) stage." (PMID 30177687, 2018). "Within the last three decades several studies followed and further unraveled the mechanisms of CD4 T cells in tumor immunity." (PMID 29032503, 2018). "Patients with MCC often exhibit oligoclonal lymphocyte-mediated and antibody-mediated immunity against MCC tumor antigens, with complex arrangements of immune cells, including B cells, CD4+ and CD8+ T cells, macrophages and regulatory T cells." (PMID 30285852, 2018). "We show that high and intermediate HER2-expressing cancer cell lines are driven toward apoptosis and tumor senescence when treated with either CD4+ Th1 cells, or Th1 cytokines TNF-α and IFN-γ, in a dose dependent manner." (PMID 29796172, 2018). "PD-1/PD-L1 signaling pathway has different effects on T cells, such as downregulation of effector T cell levels, induction of apoptosis of tumor-infiltrating T cells, and promoting CD4+ T cell differentiation into suppressive Foxp3+ Tregs." (PMID 29868037, 2018). "In the recent study, we observed a significantly increased BTLA expression on tumor-infiltrating CD4+ T cells in HCC patients." (PMID 30116751, 2018). "Pioneering in vitro studies that addressed CD4/CD8 T cells interplay emphasized the importance of both populations for tumor immunity." (PMID 29032503, 2018). "Using flow cytometric analysis, we found that the number of CD11b+Gr-1hi MDSCs and CD4+CD25+Foxp3+ Treg cells within the tumor microenvironment was remarkably reduced in CQ-treated tumor-bearing mice, compared with those in the control group." (PMID 29491374, 2018). "IL-1β is also known to enhance the production of IL-17 by CD4+ T cells, which in turn favors angiogenesis and tumor growth." (PMID 30631327, 2018). "The goals of cancer immunotherapy are to activate and expand tumor-specific CD4+ and CD8+ T cells, as an effective means of augmenting immunity and overcoming mechanisms used by tumors to evade destruction." (PMID 30214685, 2018). "Tumor-infiltrating lymphocytes (TILs) such as CD4+ and CD8+ T lymphocytes play important roles in host immune response." (PMID 29732001, 2018). "The presence of CD4+ or CD8+ T cells secreting IFN-γ in the tumor can promote the presence of M1 immunocompetent classically activated macrophages, above an M2 phenotype." (PMID 30200478, 2018). "In the tumor-bearing mice, tumor-infiltrating lymphocytes were significantly higher in Per1/2−/− mice than in wild-type mice, with a 6.9-fold and 5.4-fold increase for CD4+ and CD8+ T cell populations, respectively." (PMID 29581861, 2018). "It has now become increasingly clear that tumor-specific CD4 T cells display a complex biology and their roles are far beyond the mere task of providing helper signals to CD8 T cells." (PMID 29032503, 2018).
tumor (continued). "In summary, our findings demonstrate that CD4+ T cells reactive against a secreted tumor antigen mediate elimination of tumor cells by inducing ROS/RNS signaling by TAMs." (PMID 30083157, 2018). "As CD4+ T cells exhibit phenotypic and functional heterogeneity, different subsets are expected to play different and even opposing roles in the tumor environment." (PMID 30505306, 2018). "Th1 cytokines TNF-α and IFN-γ are increasingly recognized as critical mediators of CD4+ T-cell-driven anti-tumor activity." (PMID 29796172, 2018). "Primary mouse T cells, isolated from mice that had been adoptively transferred with OT-I (CD8+) and OT-II (CD4+) cells and vaccinated with Ova/alum, were co-cultured with B16.F10 tumor cells expressing ovalbumin (B16.F10-ova)." (PMID 30563566, 2018). "TEXs have been shown to promote tumor growth by inducing the expansion of Treg and the effector CD4+ sub-populations and by fostering their immunosuppressive capacity." (PMID 29652798, 2018). "In mice receiving the combination of 17-AAG and antigen-specific CD4+ T cells, tumor regrowth was significantly delayed, with only 2/6 mice reaching the experimental endpoints." (PMID 29481571, 2018). "Tregs can be recruited to the tumor or generated via proliferation of pre-existing Tregs in the tumor microenvironment and de novo conversion of tumor-infiltrating CD4+ lymphocytes (TIL) into pTregs." (PMID 30854331, 2018). "Their potential therapeutic relevance is further emphasized by the growing appreciation of the importance of CD4+ T cells in anti-tumor immune responses, not only in murine models but also in clinical trials." (PMID 30083157, 2018). "Lastly, the study again stressed the importance of IFN-γ in this mechanism of immunosurveillance that is released upon collaboration of tumor-specific CD4 T cells with macrophages." (PMID 29032503, 2018). "Flow cytometric analysis showed that LNT treatments facilitated tumor infiltration of CD4+, CD8+, NK1.1+ cells, monocytes, and neutrophils, while reducing tumor-associated macrophages (TAMs)." (PMID 30373628, 2018). "Taken together, these studies indicate that expression of MHC class II on tumor cells and corresponding CD4 T cell responses behave differently not only in a variety of tumor entities, but also in tumors of similar origin." (PMID 29032503, 2018). "Immune checkpoint blockade proved to be efficient when targeting CXCR2 in parallel, significantly increasing animal survival by reducing the proliferation tumor rates as well as enhancing the proportion of both CD4+ and CD8+ T cells while diminishing Tregs." (PMID 29301364, 2018). "Within the tumor draining lymph node, we observed significant decreases in granzyme B expression within the CD4+ compartment in the involution group, with granzyme B restored upon ibuprofen treatment." (PMID 30285905, 2018). "We then demonstrated SVX vaccine's high therapeutic efficacy against four different established murine tumor models, associated with its capacity to generate both specific cytotoxic CD8+ and multifunctional Th1 CD4+ T-cell responses." (PMID 30483475, 2018). "Reduced IFN-γ was seen in CD8+ and CD4+ T cells in elderly tumors compared to young tumors implying reduced anti-tumor effector T cell activity with age." (PMID 30560130, 2018). "Depletion of CD4+ cells using an anti-CD4 monoclonal antibody (anti-CD4 mAb) induces the expansion of tumor-reactive CD8+ T cells and strong antitumor effects in several murine tumor models." (PMID 30733724, 2018). "We have recently discovered that human nTreg and tumor-derived γδ Treg cells induce responder naive/effector CD4+ T-cell senescence with altered phenotypic and functions." (PMID 29339767, 2018). "Known as the most potent professional antigen presenting cells (APCs), DCs initiate all adaptive immune responses by uptaking, processing and presenting antigens including tumor antigens to activate naive antigen-specific CD4 and CD8 T cells." (PMID 30619378, 2018).